APOBEC3B (apolipoprotein B mRNA editing enzyme catalytic subunit 3B)
Diseases named in the same sentence as APOBEC3B in open-access papers (continued):
Sharing a sentence is not in itself a finding about the gene and the disease.
cancer (continued). "APOBEC3 enzymes, including APOBEC3A (A3A) and APOBEC3B (A3B), induce mutations in viral DNA, effectively inhibiting viral replication but also promoting somatic mutations in the host genome, contributing to cancer development." (PMID 40143363, 2025). "Antiviral DNA cytosine deaminases APOBEC3A and APOBEC3B are major sources of mutations in cancer." (PMID 38499542, 2024). "An intriguing actor in cancer progression and therapy resistance could also be APOBEC3B, an antiviral DNA cytosine deaminase that contributes to cancer mutation catalyzing cytosine-to-uracil deamination." (PMID 39000238, 2024). "However, it is interesting to point out that the APOBEC3B deletion polymorphism has also been associated with reduced risk for the development of certain types of cancer, such as lung cancer and ovarian cancer, in recent works in the literature." (PMID 36980505, 2023). "In particular, more than half (16/30) of cancer types have APOBEC3B-mediated mutation signatures." (PMID 35740493, 2022). "Thus, high expression levels and deaminase activity seemingly implicate APOBEC3B as the major mutator in all of the cancer cell lines analysed here, whereas analyses of extended sequence contexts and RNA-editing assays suggest a potential role for APOBEC3A." (PMID 35859169, 2022). "Considering that the APOBEC family members, including APOBEC3A and APOBEC3B, catalyze mutation and promote cancer growth, we chose the APOBEC activity-related mutational signatures, SBS2 and SBS13, to investigate the differences of the immune microenvironment among clusters." (PMID 35924239, 2022). "However, an APOBEC3B germline deletion polymorphism is associated with increased cancer risk and higher APOBEC3-associated mutation burdens in certain contexts, suggesting mutator roles for additional APOBEC3s3,21,22." (PMID 35859169, 2022). "In addition, we also analyzed the association between APOBEC3B gene alteration and clinical survival and prognosis with different types of cancers." (PMID 35918642, 2022). "In contrast, we describe here a readily translatable clinical method by which forced expression of APOBEC3B in the context of an ex vivo generated vaccine can induce an enhanced mutational load which combines with immune checkpoint blockade for very potent cancer immunotherapy." (PMID 32034147, 2020). "The authors showed that mA3 could also promote the cancer-associated microenvironment formation as does APOBEC3B." (PMID 33322756, 2020). "Recent studies have reported that APOBEC3B-associated mutagenic agents have an effect on the evolution of various cancer types and it is significantly overexpressed in a variety of cancers (such as breast, gastric, lung, and ovarian) compared to corresponding normal tissues." (PMID 32934779, 2020). "This increased expression of APOBEC3B may contribute to increased mutation rates at low irradiation dose rates and increased cancer risk from IR over long periods of time." (PMID 32880638, 2020). "As two human ssDNA cytidine deaminases APOBEC3A (A3A), APOBEC3B (A3B) and related enzymes across the spectrum of placental mammals have been shown to introduce somatic mutations into nuclear DNA of cancer genomes, we explored the mutagenic threat of A1 cytidine deaminases to chromosomal DNA." (PMID 31726973, 2019). "Interestingly, we observed that APOBEC3B expression level was positively associated with APOBEC-mutational signature in all cancer types, except for lung squamous carcinoma." (PMID 31533728, 2019). "Interestingly, APOBEC3B (A3B) a DNA cytosine deaminase, is a source of genomic DNA mutations that contributes to cancer progression and metastasis is significantly down-regulated in CEACAM6 KO cells." (PMID 31797958, 2019).
cancer (continued). "In multiple human cancer categories, increased APOBEC3B gene expression has been associated with genome-wide hypermutation and with kataegis, a mutagenic process that generates clusters of closely spaced, single-strand-specific DNA substitutions, which are predominantly C to T." (PMID 29642934, 2018). "Notably, APOBEC3B is upregulated, and its preferred target sequence is frequently mutated and clustered in several cancers especially NSCLC." (PMID 29695832, 2018). "The bimodal distribution of APOBEC3B expression is of interest since some studies previously suggested the utility of the genes with bimodally distributed expression patterns as diagnostic and prognostic biomarkers within specific cancer types." (PMID 29642934, 2018). "APOBEC3B is hypothesized to be the principal cancer driver of A3-catalyzed somatic mutations, and plays a prominent role in the genesis and evolution of various cancers." (PMID 29853799, 2018). "However, a subset of APOBEC3 proteins, most notably the nuclear-localized APOBEC3B (A3B) enzyme, is strongly implicated in causing mutations in various human cancers." (PMID 29234087, 2017). "To obtain a more global view of the role of the APOBEC3B deletion in cancer predisposition, we also conducted a comprehensive meta-analysis, considering all association studies of the deletion with breast and other types of cancer." (PMID 29100317, 2017). "Furthermore, the cancer types expressing the highest levels of APOBEC3B are likely to have the highest frequency of mutations." (PMID 28572915, 2017). "We also performed a comprehensive summary/visualization of all available reports on the association of the APOBEC3B deletion with cancer predisposition, which was obtained in our meta-analysis of association studies performed in various populations and geographic regions." (PMID 29100317, 2017). "C → T transitions in multiple human cancers have been suggested to be caused by APOBEC3B." (PMID 28572915, 2017). "Furthermore, there is a high prevalence of APOBEC3A and APOBEC3B mutation signatures in HPV-associated cancers." (PMID 28825669, 2017). "Cancer genome sequencing has implicated the cytosine deaminase activity of apolipoprotein B mRNA editing enzyme catalytic polypeptide-like (APOBEC) genes as an important source of mutations in diverse cancers, with APOBEC3B (A3B) expression especially correlated with such cancer mutations." (PMID 28977491, 2017). "Such investigations have revealed that the inactivation of mismatch repair genes, inactivating mutations of BRCA1 (ENSG00000012048), BRCA2 (ENSG00000139618), POLE (ENSG00000177084), and POLK (ENSG00000122008), or the overexpression of APOBEC3B (ENSG00000179750) causes mutagenesis in cancer." (PMID 27042257, 2016). "Expression of another APOBEC3, APOBEC3B, has been associated with increased risk of cancer." (PMID 27732658, 2016). "In addition, foci of localized hypermutations with an APOBEC3B-mediated pattern, referred to as kataegis, are often seen in these cancers and are associated with genomic rearrangements." (PMID 26083936, 2015). "Appropriate diagnostic assays will also be necessary to identify cancer cases that may benefit from APOBEC3B inhibition." (PMID 25848704, 2015). "Indeed, higher levels of L1 transposition have been documented in some types of cancer but association with APOBEC3B nullizygosity has yet to be addressed." (PMID 25848704, 2015). "An additional DNA polymerase may also be involved because C-to-A mutations have been observed in other APOBEC3B-associated cancers such as ovarian carcinomas." (PMID 25848704, 2015). "But also APOBEC3 proteins aside from APOBEC3B are reported to be implicated in cancer." (PMID 26097867, 2015).
cancer (continued). "The top five cancer types with the majority of mutations at C:G base-pairs were also among the top six datasets in terms of APOBEC3B mRNA expression, and a positive correlation between the proportion of mutations at C:G base-pairs and median APOBEC3B levels was observed." (PMID 24705290, 2014). "This consideration lets us hypothesize that levels of APOBEC3B might contribute to cancer progression as mutations acquired over time would likely be APOBEC3B level dependent." (PMID 25123150, 2014). "However, when the inflammatory response is chronic, either the mutations directly caused by APOBEC3B or the errors accumulated by the long-term high-frequency repair of UNG will become the basis for the generation of somatic mutations required for cancer evolution." (PMID 36831487, 2023). "UNG2 loss may also aggravate genomic instability in APOBEC3B expressing cancers." (PMID 32264925, 2020). "This DNA mutator hypothesis is supported by studies indicating that APOBEC3B expression is elevated in diverse forms of cancer tissues and cell lines, in contrast to its comparatively low levels in the corresponding normal human tissues spanning all major organs." (PMID 28572915, 2017). "Finally, we investigated the reason why an elevated NEIL3 expression level was associated with an increased number of somatic mutations in cancer and found that NEIL3 expression was positively correlated with the expression of APOBEC3B, a potent inducer of mutations, in diverse cancers." (PMID 27042257, 2016). "Indeed, while expression levels point towards APOBEC3B as the guilty party, the increase in cancer risk among germline APOBEC3B deletion carriers and the increased burden of APOBEC-pattern mutations attributed to APOBEC3A seen in these patients highlights key unresolved issues." (PMID 27716362, 2016). "It has since been observed that APOBEC3B expression in various cancers, including breast, lung, and cervical cancers, leads to DNA mutations predicting progression." (PMID 41373684, 2025). "Mutagenesis driven by APOBEC3A (A3A) and APOBEC3B (A3B) is evident across tumor genomes, implicating their deaminase activity in cancer initiation and progression." (PMID 41162355, 2025). "The APOBEC3A and APOBEC3B anti-viral genes show increased expression in both precancer and cancer compared to controls (p < 0.0001, p < 0.0001)." (PMID 39672307, 2024). "APOBEC3B then catalyzes APOBEC3B-mediated hypermutation formation and clonal amplification, leading to cancer development and progression." (PMID 36831487, 2023). "Upregulated APOBEC3B prefers to edit ssDNA and accumulate the APOBEC3 mutation signature in human genome and ecDNA, which promote cancer evolution and development in the proinflammatory TME." (PMID 36831487, 2023). "Accordingly, APOBEC3B has been shown to induce kataegis in cancer cell lines during telomere crisis." (PMID 36978147, 2023). "APOBEC3s are major mutagenic drivers in cancer, and APOBEC3A and APOBEC3B are likely the most significant mutators among the APOBEC3 superfamily." (PMID 36978147, 2023). "APOBEC3A and APOBEC3B are overexpressed in many cancers, and their expression correlates with a higher APOBEC3-induced mutation burden." (PMID 36978147, 2023). "In this regard, the carcinoma-specific upregulation of APOBEC3B and downregulation of APOBEC3C expression, which were found in our study, can provide strong support for cancer-associated etiology." (PMID 37121965, 2023). "Last, we studied WGS data from cancer cell lines with APOBEC3A or APOBEC3B knockout (KO) experiments." (PMID 37922356, 2023). "A common 30 kb deletion affecting the APOBEC3A and APOBEC3B genes has been linked to increased APOBEC activity and APOBEC‐related mutational signatures in human cancers." (PMID 36394079, 2023).
cancer (continued). "We also analyzed the pathogenesis or potential molecular mechanisms of APOBEC3B in different cancers by gene expression, patient survival status, protein expression, gene mutation, immune infiltration, protein interactions and cellular pathways." (PMID 35918642, 2022). "Data from other cancers have shown that APOBEC3B is the primary enzyme responsible for APOBEC signature-related mutations, whereas APOBEC3A seems to be inducing DNA damage via double-strand breaks to a higher extend than APOBEC3B17." (PMID 35902635, 2022). "APOBEC3B (A3B) has been evidenced as a DNA mutagen with consistent high expression in several cancer types." (PMID 36560657, 2022). "APOBEC3A, APOBEC3B, and APOBEC3H are most tightly linked to carcinogenesis due to their frequent expression in cancers, nuclear localization, and ability to deaminate cytidines in genomic DNA." (PMID 36970060, 2022). "Most notably, among all the APOBECs, only APOBEC3B exhibited dysregulation across all 16 cancer types." (PMID 35673559, 2022). "APOBEC3B is not only regulated by TNF-α to affect the evolution of cancer cells in the inflammatory microenvironment but also acts as a DNA dehydrogenase to effectively inhibit retroviral replication and retrotransposon migration." (PMID 36419192, 2022). "We analyzed APOBEC3B expression levels in different cancer types from TCGA using the TIMER2 website." (PMID 35918642, 2022). "This first pan-cancer study provides a comprehensive understanding of the multiple roles of APOBEC3B in different tumor types." (PMID 35918642, 2022). "Regarding cancer, at least two APOBEC3 enzymes, APOBEC3B and APOBEC3A, are prominent sources of mutation capable of influencing clinical outcomes." (PMID 36374108, 2022). "To further explore the proteomics data of APOBEC3B in patients with cancers, we conducted an analysis using the CPTAC dataset." (PMID 35918642, 2022). "Taken together, these results indicate that APOBEC3B loss can increase APOBEC3A protein levels, activity and mutagenesis in some cancer cells." (PMID 35859169, 2022). "Human apolipoprotein B mRNA editing catalytic polypeptide-like 3B (APOBEC3B), one of the seven members of the cytidine deaminase family, is upregulated in multiple cancer types." (PMID 36245972, 2022). "Random forest algorithm showed that in pan-cancer, APOBEC3B acts as the most important contributor to TCW mutation, and both APOBEC3A and APOBEC3B make the greatest contributions to AMES." (PMID 35673559, 2022). "APOBEC3B has been the primary suspect out of the APOBEC family in cancers, but its expression was very rare in our relatively large MCC tumor dataset and did not significantly correlate with LT expression." (PMID 36970060, 2022). "For example, SAR245409 is possible to demote cancer progression by inhibiting EMT through EGR-controlled TRSN, while idoxuridine is likely to inhibit the DNA Cytosine Deaminase activity of APOBEC3B and has the potential to prevent cancer development." (PMID 36124777, 2022). "Although there have been some recent cell and animal experiments indicating that expression of the gene encoding apolipoprotein B mRNA editing enzyme catalytic subunit 3B (APOBEC3B) is closely related to cancer, it still lacks pan-cancer analysis." (PMID 35918642, 2022). "Comprehensive analysis of the expression patterns, prognostic significance and relationship with tumor microenvironment of APOBEC3B at pan-cancer level will help us deepen our understanding of this enzyme." (PMID 35918642, 2022). "Several examples were identified, including germline APOBEC3B-induced mutagenesis across all cancer types." (PMID 34097189, 2021). "Of the seven APOBEC3 proteins, A3A, APOBEC3B (A3B), and APOBEC3H haplotype I (A3H-I) have been implicated in contributing to cancer mutations." (PMID 34697369, 2021).
cancer (continued). "A germline 29.5-kb deletion variant removes the 3’ end of the APOBEC3A gene and a large part of APOBEC3B, creating a hybrid gene that has been linked to increased APOBEC3 activity and DNA damage in human cancers." (PMID 34873230, 2021). "Our murine data above justifies the clinical translation of APOBEC3B-modification of tumor cells as cancer vaccines." (PMID 32034147, 2020). "Hence, the involvement of APOBEC3B in cancer cell mutations may require re-evaluation." (PMID 32880638, 2020). "This study demonstrated that APOBEC3B expression increased in a radiation dose-dependent and sustained manner after IR of the cancer cells tested." (PMID 32880638, 2020). "Expression of APOBEC3B in response to irradiation was determined in three human cancer cell lines by real-time quantitative PCR." (PMID 32880638, 2020). "Characteristic mutations, called kataegis, are detected in the genomes of cancer cells, and the observed base substitution patterns are consistent with those mediated by APOBEC3A and/or APOBEC3B." (PMID 33322756, 2020). "Analysis of donor-matched expression data further suggests that rs2142833 is a cis-expression quantitative trait locus (eQTL) for APOBEC3B at the pan-cancer level (β = 0.19, P = 2 × 10−6), consistent with cis-eQTL studies in normal cells." (PMID 32025007, 2020). "APOBEC3B has cytidine deaminase activity against ssDNA, causing a series of GC to AT mutations, and can modify the genome in somatic cells in vitro and in high APOBEC3B-expressing cancer cells." (PMID 32880638, 2020). "We focus on APOBEC3A, APOBEC3B and APOBEC3H haplotype I because they are the leading candidates as sources of somatic mutations in these and other cancers." (PMID 33292100, 2020). "Based on the functional screening of 90 cancer-associated transcription factors, we found that GATA3 is a positive regulation of APOBEC3B gene expression." (PMID 32934779, 2020). "The APOBEC3B DNA cytosine deaminase is overexpressed in many different cancers and correlates with elevated frequencies of C-to-T and C-to-G mutations in 5′-TC motifs, oncogene activation, acquired drug resistance, and poor clinical outcomes." (PMID 30723127, 2019). "This work strengthens the mechanistic linkage between active cell cycling, APOBEC3B overexpression, and cancer mutagenesis." (PMID 30723127, 2019). "Studies have shown that APOBEC3B expression is elevated in a variety of cancer tissues and cell lines, compared to the low levels in the corresponding normal human tissues." (PMID 29853799, 2018). "APOBEC3A and APOBEC3B enzymes able to target genomic DNA are involved in oncogenesis of a sizeable proportion of human cancers." (PMID 29963239, 2018). "While APOBEC3B plays a prominent role in cancer mutagenesis, several other AID/APOBEC family members also have mutagenic roles and affect DNA integrity." (PMID 29642934, 2018). "Our analysis of cancer cell line data identified associations of drug sensitivity with expression levels of APOBEC3A, APOBEC3B, REV1, and UNG genes and with abundance of sequence motifs and kataegis clusters attributed to APOBEC activity." (PMID 29642934, 2018). "In the pan-cancer analysis, APOBEC3B expression was significantly negatively correlated with sensitivity to an HSP90 (molecular chaperone heat shock protein 90) inhibitor 17-AAG (tanespimycin) (ρ = − 0.293, padj = 5.85 × 10−9, n = 536, Ntests = 1375)." (PMID 29642934, 2018). "Examination of gene expression measures in the pan-cancer dataset showed a bimodal distribution of APOBEC3B expression, whereas APOBEC3A, REV1, UNG, and FHIT had unimodal distributions of their expression measures." (PMID 29642934, 2018). "It is likely that chemical probes and therapeutic molecules targeting APOBEC3B, when used in combination with existing cancer therapies, will slow or possibly prevent metastasis, development of drug resistance, and therapy failure in human cancers." (PMID 29853799, 2018).